TUBB4A (tubulin beta 4A class IVa)
Diseases named in the same sentence as TUBB4A in open-access papers (continued):
Sharing a sentence is not in itself a finding about the gene and the disease.
prostate carcinoma (4 papers, 2022 to 2024). A carcinoma that arises from epithelial cells of the prostate gland. "In the present study, we identified, in human prostate cancers, tumor-specific high expression of TUBB4A associated with poor overall survival." (PMID 35589707, 2022). "TUBB4A expression is a potential risk factor for prostate cancers, especially for AA prostate cancers, castration-resistant prostate cancers, and neuroendocrine prostate cancers." (PMID 35589707, 2022). "Here we show that high expression levels of TUBB4A are associated with aggressive prostate cancers and poor patient survival, especially for African-American men." (PMID 35589707, 2022). "In this work, we address the role of TUBB4A in growth and metastasis of prostate cancer in vitro and in vivo, analyze the TUBB4A-interacting proteins and signaling pathways, and explore the mechanisms underlying TUBB4A-mediated tumor growth and metastasis and disparities." (PMID 35589707, 2022). "In summary, in prostate cancer cells, TUBB4A facilitates tumor growth and metastasis through MYH9-mediated GSK3β/β-catenin signaling." (PMID 35589707, 2022). "In particular, expression of TUBB4A was higher in prostate adenocarcinomas of AAs than those of EAs, suggesting an ancestral difference of TUBB4A expression for patients with prostate cancer." (PMID 35589707, 2022). "We first addressed the expression levels of TUBB4A in human prostate cancer cells, including two androgen-independent cell lines, DU145 and PC3, and one androgen-dependent cell line, LNCaP." (PMID 35589707, 2022). "Recent proteome and functional analyses reveal that, in human cancers, including prostate cancer, TUBB4A is involved with cell structural and tubulin-binding processes and resistance to chemo- and radio-therapy." (PMID 35589707, 2022). "Our results suggest an oncogenic role of TUBB4A and provide a potentially actionable therapeutic target for prostate cancers with TUBB4A overexpression." (PMID 35589707, 2022). "To evaluate the clinical relevance of TUBB4A in human prostate cancer, we conducted a bioinformatics analysis of public datasets from The Cancer Genome Atlas (TCGA)." (PMID 35589707, 2022). "Our data suggest that, during migration of prostate cancer cells, TUBB4A confers a survival advantage through protection of the nucleus and an NF-κB signaling response to DNA damage." (PMID 35589707, 2022). "In spontaneous prostate cancer mouse models, prostate-specific deletion of Tubb4a delayed tumor growth and metastasis." (PMID 35589707, 2022). "Of note, the TUBB4A gene was amplified in neuroendocrine prostate cancers, reaching 12–15% cases and in castration-resistant prostate cancers, reaching 8.57%." (PMID 35589707, 2022). "Functional analyses suggested that, during constricted migration of prostate cancer cells, TUBB4A KO changed the actin cytoskeleton, induced DNA damage, and disrupted the NF-κB signaling response and activation." (PMID 35589707, 2022). "In the present study of prostate cancer cells, TUBB4A directly interacted with MYH9 and reduced GSK3β ubiquitination and degradation." (PMID 35589707, 2022). "Our results address the role of TUBB4A in prostate cancer progression and provide a therapeutic target for patients who have tumors with TUBB4A overexpression, leading to the development of new targeted therapies of aggressive prostate cancer." (PMID 35589707, 2022). "In addition, we performed a bioinformatics analysis assessing genetic alterations of TUBB4A in primary prostate cancer samples using various datasets from 6 studies, including TCGA dataset." (PMID 35589707, 2022). "Additionally, in prostate cancer cells, TUBB4A knockout (KO) reduces cell growth and migration but induces DNA damage through increased γH2AX and 53BP1." (PMID 35589707, 2022). "In addition, in xenograft mouse models, TUBB4A KO retarded tumor growth and metastasis of prostate cancers." (PMID 35589707, 2022).
prostate carcinoma (continued). "Thus, the functional consequence of TUBB4A/MYH9 interaction in prostate cancer cells may be through two potential mechanisms." (PMID 35589707, 2022). "Immunohistochemical (IHC) analysis in The Human Protein Atlas showed that, in most prostate cancer samples (11/12 cases), TUBB4A has strong staining within tumor areas, but low or no staining in normal prostate samples." (PMID 35589707, 2022). "In most normal tissues, expression of TUBB4A is little to none, but it is highly expressed in human prostate cancer." (PMID 35589707, 2022). "TUBB4A is amplified in 14% of neuroendocrine prostate cancers and 8% of castration-resistant prostate cancers but not in primary prostate adenocarcinomas, suggesting that genetic alteration of TUBB4A contributes to development of neuroendocrine and castration-resistant prostate cancers." (PMID 35589707, 2022). "However, no Tubb4a-cKO mice developed prostate cancer, and no histologic changes were found in Tubb4a-cKO prostate versus Nkx3-1CreERT2/+ control prostate for up to 50 weeks of age." (PMID 35589707, 2022).
developmental delay (2 papers, 2018 to 2022). "Mutations in TUBB4A cause HABC with developmental delay, hypotonia, nystagmus, and deterioration of motor function." (PMID 29451896, 2018).
hereditary spastic paraplegia (2 papers, 2020 to 2025). Hereditary spastic paraplegias (HSP) comprise a genetically and clinically heterogeneous group of neurodegenerative disorders characterized by progressive spasticity and hyperreflexia of the lower limbs. "Mutations in TUBB4A are also associated with hypomyelination and atrophy of the basal ganglia and cerebellum (H-ABC), a rare hypomyelinating disease of infancy and childhood, and with an allelic clinical variant of congenital or childhood-onset hereditary spastic paraplegia." (PMID 33027950, 2020).
neuroblastoma (2 papers, 2023). Neuroblastoma (NB) is the most common solid, extracranial childhood tumor. "Conversely, a transcriptomic study on neuroblastoma SK-N-SH cells revealed that SARS-CoV-2 infection induced a downregulation of several members of building blocks of the cytoskeleton, as well as some of their regulators (i.e., TUBA1A, TUBA4A, TUBB4A, STMN4, TMSB15A, SYNPO2)." (PMID 37896797, 2023).
prostate tumor (2 papers, 2022). "TUBB4A deletion has been reported to reduce prostate tumor growth and metastasis by inhibiting the activation of NF-κB, cell cycle protein D1, and c-MYC signaling." (PMID 36713586, 2022). "Of note, increased DNA damage but decreased NF-κB, cyclin D1, and c-MYC signaling activation were evident in prostate tumors with a TUBB4A defect." (PMID 35589707, 2022). "At 35 weeks, IHC analysis showed AR+ prostate tumors in all mice, but expressions of Ki67+, c-MYC, p-IKKα/β, and p-p65 were lower in Tubb4a-cKO TRAMP versus WT TRAMP prostate tumors." (PMID 35589707, 2022). "The onset of prostate tumor and mouse death were delayed in homozygous Tubb4a-cKO (also Tubb4a-cKO) TRAMP mice compared to heterozygous Tubb4a-cKO or Tubb4a wild-type (WT) TRAMP mice." (PMID 35589707, 2022). "Our IHC analysis showed a reduced expression of CK5 in the Tubb4a/Pten-cKO versus Pten-cKO mPIN lesions but no change between Tubb4a-cKO TRAMP and WT TRAMP prostate tumors." (PMID 35589707, 2022).
breast carcinoma (1 paper, 2020). "Additionally, it may be worth mentioning that Withaferin A has been reported to bind to TUBB4A onto a binding pocket formed by Ala302, mediating growth arrest in human breast cancer cells." (PMID 32581692, 2020).
Brown syndrome (1 paper, 2024). Brown syndrome is a rare eye disorder characterized by defects in eye movements caused by abnormalities of the superior oblique tendon sheath of the superior oblique muscle. "Finally, we identified strong candidate variants in additional tubulin-encoding genes TUBB4A in isolated familial Brown syndrome and TUBB in isolated sporadic CFEOM (pedigrees 216, ENG_0678)." (PMID 38585811, 2024).
cataract (1 paper, 2025). Partial or complete opacity of the crystalline lens of one or both eyes that decreases visual acuity and eventually results in blindness. "Specifically, proteins including ACTN4, DCTN1, MYO18A, TUBA1C, TBCB, and TUBB4A, were downregulated in all cataract groups compared to controls." (PMID 41283652, 2025). "Across all cataract groups, actin and microtubule cytoskeletal proteins (ACTN4, DCTN1, TUBA1C, TBCB, TUBB4A) were significantly downregulated compared to controls, with the most marked suppression in ARC." (PMID 41283652, 2025).
cerebellar agenesis (1 paper, 2022). "The association between microcephaly, polymicrogyria and cerebellar agenesis prompted us to screen for tubulin genes (TUBA1A, TUBA8, TUBB2A, TUBB2B, TUBB3, TUBB4A, TUBB, TUBG1), which were all negative." (PMID 35162247, 2022).
Childhood onset (1 paper, 2017). Onset of disease at the age of between 1 and 5 years. "We identified a novel de novo mutation in TUBB4A in a 24-year-old female with a childhood onset dystonic syndrome with severe lower limb spasticity, dysarthria, cognitive decline and epilepsy (Patient P12)." (PMID 28334938, 2017).
colitis (1 paper, 2025). Inflammation of the colon. "Sera from four patients who developed both skin toxicity and colitis/diarrhea also showed increased autoantibodies to tubulins (TUBB2A, TUBB4A, TUBB, TUBB4B) on treatment." (PMID 40449958, 2025).
cutaneous melanoma (1 paper, 2023). A primary melanoma arising from atypical melanocytes in the skin. "In this study, we explored the prognostic value of TUBB4A for cutaneous melanoma and the potential efficacy of its inhibitors." (PMID 37439014, 2023). "However, the potential function of TUBB4A in cutaneous melanoma remains to be determined." (PMID 37439014, 2023).
generalized dystonia (1 paper, 2017). "DYT4 (TUBB4A) may present as an autosomal dominant disorder in adolescence or early adulthood with prominent laryngeal dysphonia and craniocervical, segmental, or generalized dystonia." (PMID 29110692, 2017).
glioblastoma (1 paper, 2022). The most malignant astrocytic tumor (WHO grade IV). "In human glioblastomas, silencing of TUBB4A or GLUT1 reduces glioblastoma stem cell tumor sphere formation, self-renewal, and proliferation." (PMID 35589707, 2022).
metastatic tumors (1 paper, 2022). "Of note, IHC analysis showed lower expressions of cyclin D1, c-MYC, p-IKKα/β, p-p65, and vimentin but higher expression of E-cadherin in TUBB4A KO metastatic tumors compared to scrambled metastatic tumors." (PMID 35589707, 2022). "Likewise, IHC and IF analyses confirmed increased DNA damage (γH2AX) and apoptosis (TUNEL) in TUBB4A KO metastatic tumors compared to scrambled metastatic tumors." (PMID 35589707, 2022).
prostate adenocarcinoma (1 paper, 2022). "For prostate adenocarcinoma, expression of TUBB4A was higher in tumor samples compared with that in normal prostate samples but did not change with Gleason score." (PMID 35589707, 2022). "Furthermore, we evaluated, by IHC, the protein expression of TUBB4A in 136 primary prostate adenocarcinoma samples, along with 50 samples of tumor-adjacent normal prostate." (PMID 35589707, 2022).
spasmodic dysphonia (1 paper, 2022). "General screening for mutations in TUBB4A in isolated spasmodic dysphonia is not routinely recommended, as DYT‐TUBB4A remains an exceedingly rare cause of laryngeal dystonia." (PMID 35844288, 2022).
Stroke (1 paper, 2019). Sudden impairment of blood flow to a part of the brain due to occlusion or rupture of an artery to the brain. "Our proteomics results show that many cytoskeletal proteins were present at higher-than-normal concentrations in CSF following stroke, including myosins (MYH1/4/8/9 and MYL1), and tubulins (TUBA1A/B/C, TUBA3A, and TUBB4A/B)." (PMID 30645580, 2019).
cancer (6 papers, 2020 to 2023). A tumor composed of atypical neoplastic, often pleomorphic cells that invade other tissues. "Increasing evidence has demonstrated that β-tubulin 4A (TUBB4A) plays a key role in the development and progression of several types of human cancer." (PMID 37439014, 2023). "It has been reported by scholars that ERK signaling mediates the upregulation of TUBB4A and confers cancer cells with resistance against paclitaxel." (PMID 37439014, 2023). "Many studies have provided evidence that these TFs are closely coupled with TUBB4A in several carcinomas." (PMID 37439014, 2023). "The β-tubulin family protein TUBB4A is highly expressed in cancer but it’s molecular role is unclear." (PMID 35589707, 2022). "Here, the authors show that TUBB4A is required to protect the nucleus from genomic instability during migration and that it’s over expression promotes cancer progression." (PMID 35589707, 2022). "The human microtubulin β-IVa class (TUBB4A), which pertains to the β-microtubulin family, has little or no expression in most normal tissues but is highly expressed in a variety of human cancer cell lines." (PMID 36713586, 2022). "Most cancers in Tubb4a WT or heterozygous Tubb4a-cKO TRAMP mice had progressed to poorly differentiated carcinomas (14~15/20) and lymphatic (8/20) and lung (5/20) metastases at 30 weeks of age." (PMID 35589707, 2022). "In contrast, the homozygous Tubb4a-cKO TRAMP mice developed poorly differentiated carcinomas (7/20), and few mice had lymphatic (3/20) and lung (1/20) metastases." (PMID 35589707, 2022). "However, TUBB4A is highly expressed in human cancer cell lines, including those of the prostate (e.g., PC3), breast (e.g., AN3-CA), and lung (e.g., A549) (Human Protein Atlas)." (PMID 35589707, 2022). "In DU145 cells, TUBB4A KO or MYH9 KD increased the expression of GSK3β but decreased the expression of nuclear β-catenin and its downstream targets, cyclin D1 and c-MYC, suggesting TUBB4A/MYH9-mediated GSK3β/β-catenin signaling in human cancer cells." (PMID 35589707, 2022). "RPS6KA1, WFS1, ANAPC4 and TUBB4A have not been investigated in EC prior to this, and further studies are indicated to elucidate how these genes may affect survival in cancer in general, as well as their role in EC." (PMID 32899298, 2020).
neurological diseases (5 papers, 2020 to 2025). "A spectrum of neurological disorders have been linked to variants in TUBB4A, including dystonia type 4340 and cases of isolated hypomyelination." (PMID 41315317, 2025). "A positive correlation between m1A modification and gene expression was observed, and we selected genes related to neurological diseases (Bag3, Csf1, Cyp1b1, Egfr, Flnc, Lox, Mt1, Nid2, Rab3b, and Tubb4a) for analysis, with MeRIP-RT-PCR and qRT-PCR performed to verify this phenomenon." (PMID 37173310, 2023).
tumor (4 papers, 2018 to 2025). "To determine the role of Tubb4a in spontaneous tumor metastasis, we crossed Tubb4a cKO alleles into transgenic adenocarcinoma of the mouse prostate (TRAMP) mice on a C57BL/6 background." (PMID 35589707, 2022). "Additionally, we found other abundant proteins in PDAC samples implicated in cytoskeletal dynamics, cell motility and tumor progression such as TUBB4A, SEPTIN7, ARHGDIA, THBS1, and PPP1R12A, similar to reports from the literature." (PMID 41007761, 2025). "Of note, average methylation levels in the CpG island negatively correlated with the expression of TUBB4A in tumor samples (r = −0.29, p < 0.001)." (PMID 35589707, 2022). "Expression levels of c-Myc, Ccnd1, and Vim were lower in Tubb4a/Pten-cKO versus Pten-cKO tumor cells, supporting indirect transcription regulation of these β-catenin targeted genes by TUBB4A." (PMID 35589707, 2022). "Luc imaging analysis showed that, for up to 30 days after injection, xenograft tumor growth was slower in mice injected with TUBB4A KO cells than for mice injected with scrambled cells." (PMID 35589707, 2022). "To determine the effect of TUBB4A on tumor growth in mice, we subcutaneously (S.C.)injected scrambled or TUBB4A KO DU145-luciferase (luc) cells into immunodeficient NOD-scid IL2rgnull (NSG) male mice." (PMID 35589707, 2022). "To substantiate the effect of TUBB4A on the tumor invasion-metastasis cascade and survival in the lung, we intravenously injected the scrambled and TUBB4A KO DU145 cells, respectively, into NSG male mice." (PMID 35589707, 2022). "To determine the role of TUBB4A in tumor metastasis, we extended our observation for up to 50 days after S.C. injection." (PMID 35589707, 2022). "Since expressions of c-MYC, cyclin D1, and vimentin were reduced after TUBB4A KO, we analyzed the mRNA expression of β-catenin-targeted genes c-Myc, Ccnd1, and Vim in microdissected tumor cells." (PMID 35589707, 2022). "Of note, there was higher expression of TUBB4A in AA tumor samples than in EA tumor samples." (PMID 35589707, 2022). "Likewise, prostate-specific deletion of Tubb4a reduces spontaneous tumor growth and metastasis via inhibition of NF-κB, cyclin D1, and c-MYC signaling activation." (PMID 35589707, 2022). "IHC and IF analyses confirmed TUBB4A KO in xenograft tumor cells." (PMID 35589707, 2022). "However, the role of TUBB4A in regulating cell migration as well as tumor metastasis remains elusive." (PMID 35589707, 2022). "The TUBB4A KO in tumor cells of the lung was confirmed by IF analysis." (PMID 35589707, 2022). "TUBB4A KO in metastatic tumor cells of the lung was confirmed by IF analysis." (PMID 35589707, 2022). "To elucidate the molecular mechanism of TUBB4A/MYH9-mediated tumor progression, we assessed, with DU145 cells, the role of TUBB4A/MYH9 on the GSK3β/β-catenin signaling pathway by immunoblotting analysis." (PMID 35589707, 2022). "NEK2 was altered in 22.9% of analyzed tumor samples and found interacted with the α-tubulin isoforms TUBA1A, TUBA4A, the β-tubulin isoforms TUBB, TUBB4A, TUBB4B and all the γ-tubulin isoforms." (PMID 30126203, 2018). "During the metastatic process, interaction of TUBB4A with MYH9 may protect the nucleus to avoid DNA damage and maintain tumor cell survival through the NF-κB signaling response and activation." (PMID 35589707, 2022). "H-Score quantitative analysis showed that TUBB4A was not or minimally expressed in normal prostate tissues adjacent to the tumor (NAT) but highly expressed in tumor samples." (PMID 35589707, 2022).
neurodegenerative disease (3 papers, 2015 to 2024). A disorder of the central nervous system characterized by gradual and progressive loss of neural tissue and neurologic function. "Alteration in TUBB4A (tubulin beta-4A chain), a major component of microtubules, has been associated with neurodegenerative diseases caused by hypomyelination with atrophy of the basal ganglia and cerebellum." (PMID 26636579, 2015).
TUBB4A also shares sentences with these, for which no sentence is quoted: Leukoencephalopathy (6 papers); Parkinson disease (3); Spastic paraplegia (3); Aicardi Goutières Syndrome (2); brain malformations (2); Epileptic encephalopathy (2); hepatocellular carcinoma (2); hypomyelinating leukodystrophy 6 (2); Pelizaeus Merzbacher disease (2); abetalipoproteinemia (1); adenocarcinoma of the (1); Alexander disease (1); asthma (1); astrocytoma (1); carcinosarcoma (1); cardiomyopathy (1); cerebellar ataxia (1); Cerebellar atrophy (1); cognitive decline (1); cognitive deficits (1); congenital myopathies (1); cortical dysplasia (1); dementia (1); endometrial cancer (1); epilepsy (1); frontotemporal dementia (1); gastric cancer (1); Hydrocephalus (1); Immunodeficiency 50 (1); infection (1).
A further 21 diseases each share a sentence with TUBB4A in 1 paper.